G6PD (glucose-6-phosphate dehydrogenase)
Diseases named in the same sentence as G6PD in open-access papers (continued):
Sharing a sentence is not in itself a finding about the gene and the disease.
prostate carcinoma (continued). "To identify the E3 ligase responsible for G6PD degradation, we expressed Flag-G6PD in the PTEN null prostate cancer PC3 cells and performed a mass spectrometric analysis of G6PD-associated proteins." (PMID 32312982, 2020). "To avoid nonspecific off-target effects of 6-AN, we manipulated the PPP activity by overexpressing or knocking down its rate-limiting enzyme G6PD in the PTEN null prostate cancer PC3 cells." (PMID 32312982, 2020). "GM+CTCs (marked by PGK1/G6PD) were detectable in 64.8% (35/54) of prostate cancer patients, accounting for 46.5% (134/288) of total CTCs." (PMID 29954422, 2018). "Clinical data suggested that the glucose-6-phosphate dehydrogenase (G6PD), the rate-limiting enzyme in the pentose phosphate pathway, is upregulated in prostate cancer." (PMID 29156751, 2017). "Taken together, these results highlight the regulation of NAPDH and ROS levels by androgens and the importance of G6PD in maintaining prostate cancer cell redox homeostasis." (PMID 24861463, 2014). "Accordingly, in two separate mouse models of Pten deletion/elevated mTOR signaling, Pb-Cre;Ptenf/f and K8-CreERT2;Ptenf/f, G6PD levels correlated with prostate cancer progression in vivo." (PMID 24861463, 2014). "Correspondingly, clinical data suggest glucose-6-phosphate dehydrogenase (G6PD), the rate-limiting enzyme of the pentose phosphate pathway, is upregulated in prostate cancer." (PMID 24861463, 2014). "Taken together, our data suggest that AR signaling can promote prostate cancer through the upregulation of G6PD and therefore, the flux of sugars through the pentose phosphate pathway." (PMID 24861463, 2014). "Accordingly, G6PD expression was increased upon androgen treatment in hormone-sensitive prostate cancer cell lines." (PMID 24861463, 2014). "Furthermore, it has been reported that prostate cancer cells with bone metastasis exhibit increased G6PD expression in response to cytokine secreted by bone marrow stromal cells residing in the bone microenvironment." (PMID 41514554, 2025). "Therefore, this study aimed to evaluate the potential of G6PD activity level as a biomarker for predicting bone metastasis in patients with prostate cancer." (PMID 41514554, 2025). "Indeed, the expression and activity of G6PD increase with prostate cancer progression and are particularly elevated in bone metastatic prostate cancer." (PMID 41514554, 2025). "Androgen receptor signaling was reported to promote the PPP through mTOR-mediated upregulation of G6PD in human prostate cancer cell lines, and G6PD expression was closely correlated with prostate cancer progression using two animal models of Pten deletion/elevated mTOR pathway." (PMID 37802999, 2023). "In keeping with this, it was found that knockdown of G6PD could sensitize prostate cancer cells to cisplatin and docetaxel chemotherapy." (PMID 35213227, 2022). "Furthermore, we show how elevated G6PD contributes to prostate cancer growth and survival within this unique tumor microenvironment." (PMID 35213227, 2022). "We therefore used a xenograft model in nude mice to investigate whether targeting G6PD inhibits prostate cancer tumor growth in vivo." (PMID 35213227, 2022). "This suggests that pharmacological inhibition of G6PD is still effective in the prostate cancer–bone microenvironment and can overcome the increase in G6PD expression induced by the bone microenvironment, providing further support for targeting the PPP in prostate cancer bone metastasis." (PMID 35213227, 2022). "In the current study, we use a well-characterized model of prostate cancer bone disease, demonstrating that knockdown of G6PD expression in prostate cancer cells resulted in a significant reduction in tumor burden within bone in vivo, associated with an increase in tumor cell apoptosis." (PMID 35213227, 2022).
prostate carcinoma (continued). "Our data suggest that G6PD expression is elevated in the bone microenvironment and plays a key role in prostate cancer cell growth; however, the function of G6PD in prostate cancer growth within the bone microenvironment in vivo is unknown." (PMID 35213227, 2022). "With the recent recognition of the importance of metabolic reprogramming in cancer progression, our study reveals a metabolic mechanism by which the bone microenvironment supports prostate cancer growth and survival, by up-regulation of G6PD, the rate-limiting enzyme of the PPP." (PMID 35213227, 2022). "Our analysis showed that G6PD expression was significantly up-regulated as prostate cancer progressed from treatment-naïve to castrate-resistant, suggesting that G6PD may be up-regulated in response to disease progression and/or treatment." (PMID 35213227, 2022). "In prostate cancer, while increased G6PD expression has been observed in a murine model of prostate cancer, the function of G6PD either in the primary tumor or in a metastatic setting in vivo remains unclear." (PMID 35213227, 2022). "We therefore investigated whether alterations in G6PD can sensitize prostate cancer cells to chemotherapy." (PMID 35213227, 2022). "To understand the mechanism(s) behind G6PD activation, we hypothesized that AR signaling, elevated in the majority of prostate cancers, regulated the levels of this key enzyme." (PMID 24861463, 2014). "In prostate cancer, the regulation and functional role of G6PD is unclear." (PMID 24861463, 2014). "We hypothesized that G6PD could play a role in prostate cancer cell proliferation and further hypothesized that this could be regulated by AR, a central factor in prostate cancer." (PMID 24861463, 2014). "While we focused on G6PD and its role in prostate cancer, other groups have demonstrated that additional enzymes involved in the pentose phosphate pathway may be altered in cancer." (PMID 24861463, 2014). "Interestingly, comparison of hormone-sensitive prostate cancer cell models to their CRPC-derivative models often demonstrated higher basal G6PD levels in the CRPC models, perhaps reflecting the high basal levels of AR activity in these cells." (PMID 24861463, 2014). "In addition, prostate cancer cells exhibit upregulation of G6PD within the bone microenvironment." (PMID 41514554, 2025). "Bone marrow stromal cells were found to up-regulate G6PD expression via interleukin-6 (IL-6) secretion, and targeting G6PD either pharmacologically or genetically could inhibit prostate cancer proliferation, migration, mesenchymal phenotype, and sensitivity to chemotherapy." (PMID 35213227, 2022). "In view of the known role of the PPP in cellular redox balance and the importance of ROS generation in chemotherapeutic response, we investigated whether targeting G6PD in bone metastatic prostate cancer cells could influence redox homeostasis and chemotherapy response." (PMID 35213227, 2022). "Importantly, G6PD levels remained high during progression to castration-resistant prostate cancer." (PMID 24861463, 2014). "Bone metastatic PC3 prostate cancer cells were found to have higher levels of the antioxidant glutathione (GSH) when compared to non–bone metastatic LNCaP cells, along with higher G6PD." (PMID 35213227, 2022). "The TRIM21 mRNA and protein levels were upregulated when the WT PTEN, but not the phosphatase-dead CS PTEN, was re-expressed in the PTEN null prostate cancer PC3 cells, accompanied by decreased G6PD levels." (PMID 32312982, 2020). "Similar to our findings in the isogenic mES cell lines, we observed significantly higher levels of total G6PD protein and lower levels of Trim21 mRNA in the Pten null T-ALL and prostate cancer models compared with their WT littermates." (PMID 32312982, 2020). "Even considering that the prevalence of bone metastasis in the overall prostate cancer group is not high, the use of G6PD as a standalone predictor for bone metastasis is limited." (PMID 41514554, 2025).
prostate carcinoma (continued). "G6PD expression increases with advancing disease stage, and is particularly elevated in bone metastatic prostate cancer cells compared to benign prostate tissue or non-bone metastatic prostate cancer cells." (PMID 41514554, 2025). "Emerging research indicates that the pentose phosphate pathway (PPP), particularly through its rate-limiting enzyme glucose-6-phosphate dehydrogenase (G6PD), plays a critical role in the progression of prostate cancer to bone metastases, correlating with a poorer prognosis." (PMID 38893112, 2024). "A neutralizing antibody to IL-6 was found to significantly reduce G6PD expression and STAT3 phosphorylation in prostate cancer cells treated with HS5 CM, demonstrating that bone marrow stromal cell–derived IL-6 can drive up-regulation of G6PD in prostate cancer cells." (PMID 35213227, 2022). "The rate-limiting enzyme of the PPP, G6PD, was first suggested as a biomarker for prostate cancer over 30 years ago, with increased G6PD activity noted in patients with prostate cancer as compared to benign prostatic hyperplasia (BPH)." (PMID 35213227, 2022). "Further, PGK1/G6PD-marked hypermetabolic CTCs (GM+CTCs, i.e. DAPI+CD45−PGK1/G6PD+ cells) potentially represent a more accurate marker than EMT-CTCs for the diagnosis of metastasis in prostate cancer patients." (PMID 35992829, 2022). "Similarly, the PHLDA3 mRNA and protein levels were increased upon G6PD knockdown and decreased upon G6PD overexpression in the human PTEN null PC3 prostate cancer cells, indicating that PHLDA3 expression is negatively regulated by the PPP." (PMID 32312982, 2020). "Gene expression analysis of CTCs of prostate cancer patients have revealed altered expression levels of eight metastasis-related metabolic genes, such as phosphoglycerate kinase 1 (PGK1) and glucose-6-phosphate dehydrogenase (G6PD) responsible for optimal glucose metabolism in CTCs." (PMID 33924671, 2021). "Furthermore, additional studies are needed to determine whether G6PD activity, when combined with other non-invasive biomarkers such as PSA, ALP and osteopontin, can improve the accuracy of predicting bone metastasis in prostate cancer patients." (PMID 41514554, 2025). "However, a limitation remains in that G6PD levels may also increase in the presence of other undetected malignancies not related to prostate cancer." (PMID 41514554, 2025). "It is intriguing to speculate whether overexpression of G6PD in nonmetastatic prostate cancer would be sufficient to drive bone metastasis, a challenging experiment due to the lack of well-characterized in vivo models in which prostate cancer spreads from the primary tumor site to the bone." (PMID 35213227, 2022). "Following the culture of non–bone metastatic prostate cancer cells (LNCaP) in the presence and absence of bone marrow stromal cells (HS5), we demonstrated a time-dependent increase in G6PD expression." (PMID 35213227, 2022). "We confirmed silencing of G6PD by immunobloting in LNCaP, C4-2, CWR22 and 22Rv1 cells and demonstrated that, like 6AN, molecular inhibition of G6PD decreased prostate cancer cell growth in the presence or absence of androgens in both hormone-sensitive and castration-resistant cell models." (PMID 24861463, 2014).
Sepsis (22 papers, 2009 to 2025). Sepsis is defined as life-threatening organ dysfunction caused by a dysregulated host response to infection. "Neutrophil dysfunction can attenuate the oxidative burst and produce spuriously low results in sepsis-induced immunoparalysis, bone marrow suppression, or metabolic disorders such as glucose-6-phosphate dehydrogenase (G6PD) deficiency." (PMID 41154281, 2025). "In one study of African-American trauma patients, those with G6PD A- deficiency were at increased risk for prolonged systemic inflammatory response syndrome, septicemia, and respiratory and wound infections." (PMID 38938571, 2024). "In G6PD-deficient infants in Saudi Arabia, where the Mediterranean variant predominates, an increased risk of severe infection and sepsis was seen in childhood, especially with catalase-positive organisms." (PMID 38938571, 2024). "The current analysis of genotypes showed that a boy born at home who was seen at day 2, had fever, clinical signs of sepsis and died shortly afterwards, was hemizygous for Canton mutation (he tested G6PD deficient by FST)." (PMID 36962413, 2022). "Studies have shown that patients with G6PD are more likely to develop sepsis, so treatment for patients with G6PD deficiency needs to be more cautious." (PMID 36160421, 2022). "One female term neonate who was heterozygous for G6PD*Mahidol allele had clinical signs of sepsis and severe NH at the day 7 visit (TSB = 1,072 μmol/L) and was referred for exchange transfusion at the local Mae Sot Hospital." (PMID 36962413, 2022). "Sepsis usually coexists with exposure to exogenous agents that predispose the G6PD deficient infants to severe NNJ and ABE." (PMID 25884571, 2015). "Confounders were observed in 23% G6PD deficient infants, including sepsis, prematurity and Rh incompatibility." (PMID 22906047, 2012). "Similar confounders were present in three neonates with G6PD c.563C > T variant (pre-term n = 1, preterm and sepsis n = 1 and ABO incompatibility n = 1)." (PMID 22906047, 2012). "Given the role of G6PD in phagocyte effector function, in the 1960s, it was theorized that G6PD deficiency might impact susceptibility to sepsis and meningitis." (PMID 38938571, 2024). "In reality, the expression of the enzyme is high in leukocytes and other immune cells, and, recently, G6PD deficiency has been found to be involved in several disorders beyond blood diseases, including sepsis, neonatal hyperbilirubinemia, and cardiovascular disease, especially in the elderly." (PMID 34884340, 2021). "The other possible mechanisms that might explain the increased prevalence of sepsis among G6PD-deficient neonates was increased serum iron concentration due to lysis of erythrocytes." (PMID 27974910, 2016). "This is likely to be an issue in G6PD-deficient individuals because an inability to maintain endothelial homeostasis has been linked to both acute and chronic inflammatory endothelial activation and has relevance to pathologies as diverse as cardiovascular disease and sepsis." (PMID 38938571, 2024). "G6PD has been verified to be upregulated by Nrf2, which leads to metabolic reprogramming and alleviates ferroptosis in sepsis-induced vascular leakage." (PMID 37149513, 2023). "Macrophages with a G6pd mutation show decreased PPP activity and increased bacterial burden and worse survival outcomes in an animal model of sepsis." (PMID 31555665, 2019). "Of them the closest by 7 alleles (adk, aroA, deoD, pgi, g6pd, mdh, gdhA) to strains of P. multocida, isolated from the saigas in Kazakhstan was ST64 (id: 193) isolated from the bovine with septicaemia in Hungary." (PMID 30744550, 2019). "NAFLD was reported to upregulate 11β-HSD1, 11β-HSD2, and G6PD, thereby enhancing the production of corticosterone, which could contribute to combat sepsis shock." (PMID 34938184, 2021). "Furthermore, newborn infants born with a G6pd deficiency are more susceptible to sepsis due to a lack of leukocyte bactericidal activity." (PMID 31555665, 2019).
Sepsis (continued). "It associates directly with TDRD9 and indirectly with SLC16A3 in pediatric sepsis, through MTF1, CD82, and G6PD." (PMID 32318053, 2020). "The main risk factor for jaundice was identified as prematurity either with or without sepsis in G6PD normal infants." (PMID 22906047, 2012). "The exact mechanisms of increased susceptibility of sepsis in G6PD deficient neonates are not clear and require further investigations, but one hypothesis is that reducing the synthesis of ROS resulting from the lack of NADPH due to G6PD deficiency may be one of these mechanisms." (PMID 27974910, 2016).
bladder cancer (19 papers, 2007 to 2026). "Chen and partners found that knocking down G6PD promotes the accumulation of reactive oxygen species, leading to cell death in bladder cancer cells, thereby reducing disease progression and improving prognosis." (PMID 41505248, 2026). "Modulation of G6PD was proven to affect bladder cancer via ROS accumulation and the AKT pathway in vitro, and knockdown of G6PD reduces ROS accumulation and enhances apoptosis of bladder cancer cells." (PMID 38098504, 2023). "ZA inhibits G6PD by decreasing its expression in bladder cancer cells which leads to reduced proliferation of cancer cells." (PMID 35628385, 2022). "Zoledronic acid was proven to block Ras signaling and reduce the stability of TAp73, thereby inhibiting the expression of G6PD in bladder cancer cells." (PMID 35207558, 2022). "For instance, high-G6PD-expressing bladder cancer cells displayed higher sensitivity to 6-AN compared with lower-G6PD-expressing cells." (PMID 35806424, 2022). "This is important, since an increased ROS level coupled to Akt pathway suppression also inhibited glucose-6-phosphate dehydrogenase (G6PD), a rate-limiting enzyme of the pentose phosphate pathway, weakening survival of bladder cancer cells." (PMID 34073079, 2021). "Patients with lower G6PD expression in tumor resection have a better survival rate compared with bladder cancer patients with higher G6PD expression." (PMID 32903581, 2020). "Mitigation of the Ras–TAp73–G6PD pathway by ZA results in the inhibition of G6PD, leading to retardation of bladder cancer cell proliferation." (PMID 31500396, 2019). "The stability of TAp73, the activator of G6PD, is decreased in ZA-treated bladder cancer cells through inhibition of Ras activity." (PMID 31500396, 2019). "In bladder cancer cell metabolism, increased expression of G6PD and fatty acid synthase are observed." (PMID 31500396, 2019). "This suggests that ZA can inhibit TAp73 stability and decrease G6PD activity via blocking Ras signaling in bladder cancer cells." (PMID 31500396, 2019). "In addition, G6PD inhibitor 6-AN can also significantly reduce the proliferation of bladder cancer cells and exert a synergistic anti-tumor effect with cisplatin." (PMID 35207558, 2022). "ZA inhibits cell proliferation by decreasing the expression of G6PD in bladder cancer cells." (PMID 31500396, 2019). "High expression and activity of G6PD have been verified in cisplatin-resistant ovarian cancer (C13, SKOV3/DDP), renal cancer (ccRCC), non-small cell lung cancer (A549/DDP), and bladder cancer (T24, TCCSUP) cell lines." (PMID 35628385, 2022). "In bladder cancer, a study showed that GAPDH, G6PD and HMBS were significantly changed between malignant and nonmalignant tissues." (PMID 17640361, 2007). "G6PD was suggested to be an inappropriate internal control in qRT-PCR studies of estrogens effects in fish and it also showed significant differences in expression between malignant and nonmalignant pairs (at least p < 0.04) of human bladder cancer." (PMID 18573215, 2008).